PDPN (podoplanin)
Diseases named in the same sentence as PDPN in open-access papers (continued):
Sharing a sentence is not in itself a finding about the gene and the disease.
tumor (continued). "Most studies examining the role of PDPN in cancer have focused on cancer cells, but some papers exploring fibroblast-specific PDPN effects have found that PDPN+ CAFs support tumor growth and immunosuppression in the tumor microenvironment." (PMID 34879110, 2021). "The interaction between CLEC-2 and podoplanin-expressing tumor cells promote angiogenesis, tumor growth and metastasis." (PMID 34177942, 2021). "The expression of NANOG and OCT4 was evaluated by immunohistochemistry in 122 cases, SOX2 in 121 cases, Nestin in 93 cases and PDPN in 85 cases in which representative tumor tissue was available." (PMID 34201050, 2021). "Using anti-PLAG-neutralizing antibodies, the function of PLAGs was confirmed in CLEC-2 binding, platelet aggregation, and tumor emboli formation indicating that simultaneous inhibition of PLAGs is efficient to block PDPN-mediated tumor growth and metastasis." (PMID 34322381, 2021). "As a result, platelets and tumor cells firmly cohere to form stable TCPAs connected by three different receptor pairs: Clec-2 and podoplanin, P-selectin and PSGL-1, and integrin αIIbβ3 via fibrin to integrin αVβ3." (PMID 33937274, 2021). "In the two-stage skin carcinogenesis model, epidermal ablation of PDPN reduced tumor growth and invasion." (PMID 34987523, 2021). "PDPN is a type I transmembrane sialomucin-like glycoprotein located on the surface of many tumor cells, including squamous cell carcinoma, seminoma and brain cancer cells." (PMID 34322381, 2021). "C-type lectin-like receptor 2 (CLEC-2) is a platelet activation receptor for the membrane protein podoplanin, which is expressed on some types of tumor cells and lymphatic endothelial cells." (PMID 34362190, 2021). "CLEC-2/podoplanin interaction facilitates tumor metastasis and blood/lymphatic vessel separation and normal lung formation during embryonic development." (PMID 34362190, 2021). "Adding to this complexity, it was recently shown that in 4T1 tumours, FAPα+PDPN+ CAFs are capable of producing nitric oxide (NO), controlling the proliferation of effector T-cells, thus helping to create an immunosuppressive TME in TNBC." (PMID 34016130, 2021). "An average of 40% of CAFs in each tumor were PDPN positive, and while lymphatic endothelial cells also express PDPN, CAFs had many more molecules per cell." (PMID 34879110, 2021). "In athymic nude mice, injection of PDPN-overexpressing cancer cells generated bigger tumors, while silencing of PDPN suppressed tumor growth." (PMID 34987523, 2021). "The functions of PDPN in human fibroblasts and the tumor microenvironment remain largely uncharacterized, in part due to a limited understanding of the landscape of PDPN co-receptors on the cell surface." (PMID 34879110, 2021). "In tumor-bearing mouse models, either ablating PDPN gene or blocking PDPN by monoclonal antibody (mAb) injection effectively suppressed platelet aggregation, supporting that PDPN is crucial for TCIPA formation." (PMID 34987523, 2021). "As there is no single marker that identifies lymphatic vessels specifically in human tumor tissues, we identified LECs by co-staining of Prox-1 and Podoplanin." (PMID 33868585, 2021). "Surprisingly, PDPN expression levels in FRCs under tumor conditions were, in fact, higher than in controls." (PMID 34706240, 2021). "Among various possible tumor cell-platelet interactions, the interaction of PDPN with C-type-lectin-like-2 (CLEC-2) on the platelet surface has gained significant attention." (PMID 32581653, 2020). "Monoclonal antibodies targeting PDPN expressed in human tumor cells showed obvious anti-tumor effects in preclinical studies using mouse models." (PMID 33238582, 2020). "A previous study has reported that PDPN is related to tumor invasion and metastasis, and it was also reported that the PDPN expression density of tumor cell lines derived from metastatic lesions was higher than that of the primary tumor." (PMID 33238582, 2020).
tumor (continued). "Previously, we generated a cancer-specific mouse–dog chimeric anti-PDPN antibody, P38Bf, which specifically recognizes PDPN expressed in canine tumor cells." (PMID 33238582, 2020). "PDPN has also been reported to express frequently at the peripheral site of tumor nest, especially among squamous tumors including lung squamous cancer." (PMID 32408907, 2020). "Based on these strategies, immunotherapy using a therapeutic antibody targeting PDPN expressed on tumor cells is considered to be a promising therapy for patients with PDPN-positive tumors." (PMID 33238582, 2020). "Since both podoplanin and CD44 have been described as components of tumor invasion-related invadopodia, we are currently investigating the role of podoplanin interaction with CD44s and CD44v in invadopodia formation and activity." (PMID 33003440, 2020). "Podoplanin (D2-40) is a mucin-type transmembrane glycoprotein, expressed in lymphatic endothelial cells and other cells, such as macrophages and tumor cells." (PMID 32516408, 2020). "In human SCC, PDPN expression has been related with increased tumor progression and metastasis rates." (PMID 32380790, 2020). "These authors found that in patients with low tumor budding grade, considered (histological) morphometric findings of invasiveness, the presence of podoplanin was a significant predictor of neck lymph node metastasis." (PMID 32932638, 2020). "In human SCC, PDPN promotes tumor cell migration and invasion by cytoskeleton remodeling via Rho signaling." (PMID 32380790, 2020). "As expected, the study indicated that podoplanin expression favors fibroblast migration in the tumor stroma." (PMID 32604738, 2020). "Podoplanin expressed in tumor cells facilitate hematogenous metastasis by binding to platelet CLEC-2." (PMID 33003440, 2020). "Platelets bind tumor cells via C-type lectin-like immune receptor 2 (CLEC-2) interaction with podoplanin, which is expressed at the invasive front of many tumors and associated with poor outcome in various cancer types." (PMID 32244723, 2020). "Further researches should be focused on unified cut-off standard to detect the expression of PDPN, and its unique expression type (P-type or non P-type) in tumor, thus to undermine the mechanism of PDPN in squamous lung cancer progression." (PMID 32408907, 2020). "Despite this limitations, there are no studies to date evaluating the relationship between CAFs and the tumour expression of PDPN in different forms of HNSCC, although this relationship has already been demonstrated in other types of cancer." (PMID 31967978, 2020). "In other forms of HNSCC this association is variable, whereas a similar relationship has been observed between tumour expression of PDPN with low survival and infiltrating phenotype in laryngeal and oesophageal SCC." (PMID 31967978, 2020). "In HSA tumor tissue, however, anti-PDPN staining was robust in the cytoplasm of tumor cells encircling the collagen fibrils (arrow)." (PMID 32571313, 2020). "Our results for OA are consistent with these previous observations for tumour cells (regarding PDPN and MMP activity) and for RA (regarding PDPN and inflammation)." (PMID 32326143, 2020). "Our present results further indicate that the invasion capacity of tumor cells is synergistically controlled by PDPN levels and EMT inducers." (PMID 32581653, 2020). "Previously, we and others have demonstrated that elevated levels of PDPN in the tumor tissues of patients with esophageal squamous carcinoma, especially in cells at the invasive edge, are correlated with poor prognosis after esophagectomy." (PMID 32581653, 2020). "We found that keratinocyte-expressed podoplanin is dispensable for tumor initiation and multiplicity in a mouse chemical skin carcinogenesis model." (PMID 32599908, 2020).
tumor (continued). "Since anti-human PDPN antibodies including NZ-1 also recognize normal cells such as lymphatic endothelial cells, a cancer-specific mAb (CasMab) that specifically recognizes human PDPN in tumor cells was established in 2014." (PMID 32326079, 2020). "This is the first reported clinical trial of anti-PDPN antibody therapy using spontaneously occurring canine tumor models." (PMID 33238582, 2020). "In OC, podoplanin has been reported to be highly expressed in tumor cells at the invasive front, which correlated with the extent of lymphatic endothelial cell proliferation." (PMID 32533757, 2020). "These tumor-stroma interactions are facilitated by the glycoprotein podoplanin and the extracellular matrix protein tenascin-C expressed by CAFs." (PMID 33747899, 2020). "Release of PDGF and TGF-β during podoplanin-positive tumor cell-induced platelet aggregation is suppressed by anti-podoplanin mAbs." (PMID 32532126, 2020). "Nevertheless, beyond the potential interaction with CLEC-2, the roles of PDPN in platelet-induced tumor cell EMT and invasibility remains poorly understood." (PMID 32581653, 2020). "We next investigated the potential contribution of tumor cell expressed podoplanin to the immune cell accumulation in tumors." (PMID 32599908, 2020). "A number of studies have shown that PDPN expression in cancer cells promotes tumor cell proliferation and invasion." (PMID 32571313, 2020). "The transmembrane glycoprotein podoplanin is another marker that has been shown to be expressed in the dense pancreatic stroma surrounding the tumour nests." (PMID 33060625, 2020). "Actually from our results, PDPN do have significant correlations with tumor better differentiation in LUSC (HR = 2.14, 95% CI = 1.34–3.43, P = 0.002)." (PMID 32408907, 2020). "IHC analysis found that PDPN was robustly expressed in transformed endothelial cells in certain HSA tumor samples." (PMID 32571313, 2020). "A coordinate upregulation of podoplanin with CD44s and CD44v is also observed in vivo during malignant progression of mouse-skin chemical carcinogenesis." (PMID 33003440, 2020). "Based on this, PDPN-neutralizing antibodies have been developed and, in fact, such antibodies have been shown to suppress the tumor progression of human SCC in a mouse model." (PMID 32380790, 2020). "PDPN is often identified to express at the leading edge of a tumor, suggesting that it contributes to metastasis and infiltration of the cancer cells." (PMID 32858947, 2020). "In the present study, we investigated the role of epidermal cell expressed podoplanin in tumor initiation and growth in the two-step mouse chemical skin carcinogenesis model, using epidermis-specific podoplanin knockout (K5-Cre;Pdpnflox/flox) mice." (PMID 32599908, 2020). "Results show that, while PDPN or LAMA4 transcripts were either absent or weakly expressed in normal spleen, LAMA4 was significantly expressed in all three tested HSA tumor samples while PDPN was robustly expressed in one (C356) of the three HSA samples." (PMID 32571313, 2020). "A high podoplanin and tenascin-C expression in the stroma of PCa biopsies strongly correlates with tumor stage, lymph node metastasis, and poor prognosis." (PMID 33747899, 2020). "Although the molecular mechanism by which dPDPN knockdown leads to G2/M cell cycle arrest was not clarified in this study, we have uncovered a novel role for PDPN in tumor cells." (PMID 32380790, 2020). "In any case, the levels of PDPN seem to contribute positively to the malignant characteristics of tumor cells." (PMID 32581653, 2020). "Podoplanin mediated tumor cell-platelet aggregation promotes the release of platelet derived TGF-β1, which is critical for EMT, invasion and metastasis." (PMID 32532126, 2020). "Overall, this study demonstrates that dPDPN is expressed in various types of canine tumors and that dPDPN silencing suppresses cell viability through apoptosis and cell cycle arrest, thus providing a novel biological role for PDPN in tumor progression." (PMID 32380790, 2020).
tumor (continued). "Both tumor cells and CAFs overexpress podoplanin, which is a type I transmembrane mucin-like sialoglycoprotein." (PMID 32532126, 2020). "In particular, the lectin MASL shows dynamic abilities to target PDPN and normalize the morphology and phenotype of tumour cells." (PMID 32326143, 2020). "The CATS also showed a high tumor podoplanin expression, which correlated with a laboratory measured hypercoagulability state, intratumoral thrombosis, and increased VTE risk." (PMID 32466430, 2020). "Remarkably, tumor-derived microvesicles expressing podoplanin have been observed in the plasma of patients with pancreatic and colorectal cancer." (PMID 31337034, 2019). "All tumour samples were successfully stained and a QS was estimated for all 39 cases for E‐cadherin, β‐catenin, and podoplanin." (PMID 31452946, 2019). "In the study group, positive podoplanin expression in the cell membrane/cytoplasm of the tumor cells was observed in 45/60 (75%) cases." (PMID 31508790, 2019). "The expression of podoplanin correlated inversely (p=0.017) with the degree of differentiation of the tumor." (PMID 31508790, 2019). "The binding of CD9 to tumor cells via podoplanin abolishes its platelet aggregation activity and inhibits podoplanin-induced metastasis." (PMID 30736372, 2019). "Not only was it key to decipher the important role of tumour cell-induced platelet activation via the podoplanin-CLEC-2 axis, but it has also been used successfully to experimentally effect haematogenous metastasis." (PMID 30823637, 2019). "Among the potential roles of podoplanin, platelet activation has recently gained interest as a potential key mechanism for the malignancy of podoplanin-positive tumor cells." (PMID 31553741, 2019). "Podoplanin expression contributes to a pro-migratory phenotype in MSCs found in the perivascular space, lymphoid tissues and tumours." (PMID 30745334, 2019). "In accordance, CD31 staining of primary tumor sections revealed only minimal difference between the two groups, whereas Lyve1 and Podoplanin staining of lymphatics was significantly increased in the absence of Rbpj." (PMID 30604758, 2019). "Numbers of VV and LV were evaluated using immunohistochemistry detecting CD34 and podoplanin, respectively, and correlated to clinical data, biochemical recurrence (BR), and proteins analyzed in tumor cells." (PMID 31547460, 2019). "Podoplanin is a type of transmembrane sialoglycoprotein, which plays an important role in tumor progression and metastasis." (PMID 31508790, 2019). "Much of the evidence linking podoplanin with cellular migration has been gleaned from studies on tumour or lymphoid stromal cells." (PMID 30745334, 2019). "Miyashita el al. revealed that the high clonal expansion capacity of podoplanin-positive tumor-initiating cell populations was the result of reduced cell death by podoplanin-mediated signaling." (PMID 31321241, 2019). "Soluble podoplanin can be generated after proteolytic cleavage of the extracellular domain and entry into the blood circulation, or can be secreted by both tumor and stromal cells as a full-length protein attached to extracellular vesicles." (PMID 30736372, 2019). "There are a number of functional studies that addressed the role of podoplanin-expressing CAFs on tumor development and progression." (PMID 30736372, 2019). "In accordance with another study of ACC, we also saw a significantly better prognosis for tumours with high expression of podoplanin." (PMID 31452946, 2019). "For example, neutralizing Abs targeting either podoplanin or CLEC-2 are able to block platelet aggregation and metastasis induced by podoplanin-expressing tumor cells." (PMID 30736372, 2019). "There was a significant inverse correlation between the expression of SOX2 and podoplanin with the tumor grade (p=0.002 and p=0.017, respectively)." (PMID 31508790, 2019).
tumor (continued). "Podoplanin has been reported to enhance tumour invasion by enhancing cell motility through interaction with actin in the cytoskeleton via proteins such as ezrin, radixin, and moesin." (PMID 31452946, 2019). "On tumor sections obtained on D5 post tumor inoculation (2 days after tamoxifen delivery), the large majority of Prox1+ cells co-localized with Lyve1 and Podoplanin expressing lymphatics in the periphery of the tumor." (PMID 30604758, 2019). "Podoplanin is seen in the tumor cells themselves, as well as in stromal cells, particularly in cancer-associated fibroblasts (CAFs)." (PMID 30736372, 2019). "In LSCC, the altered tumor microenvironment caused by oxidative stress induced by the stimulation of NNK can potentially cause the dysregulation of ERBB4, PDPN, and EMR2 signaling pathways." (PMID 31217907, 2019). "We found that SZ168 not only suppresses PDPN-induced platelet aggregation in vitro but also inhibits tumor growth and metastasis in both mouse (CHO/hPDPN) and human (C8161) cancer cells." (PMID 31208371, 2019). "A recent study in stage I lung carcinoma has unveiled the role that PDPN+ CAFs have in attenuating anti-tumor immunity by decreasing the CD8/Foxp3 T cell ration, supporting monocyte recruitment and their differentiation into TAMs." (PMID 31462327, 2019). "The interaction between tumor cell PDPN and platelet CLEC-2 drives tyrosine phosphorylation of the Src family kinases (Syk) and phospholipase C gamma 2 (PLCγ2), resulting in platelet activation and aggregation." (PMID 31208371, 2019). "Subcutaneous tumor formation was confirmed by H&E staining, and lung micro-metastasis foci and subcutaneous tumors were confirmed by immunostaining of PDPN using SZ168 and 18H5 antibodies." (PMID 31208371, 2019). "Studies have also suggested that podoplanin–CLEC-2-induced platelet activation promotes tumour growth and facilitates epithelial-to-mesenchymal transition." (PMID 30745334, 2019). "Podoplanin (PDPN), a transmembrane O-glycoprotein, is up-regulated in many tumors and is involved in tumor metastasis and malignant progression." (PMID 31208371, 2019). "Podoplanin is a mucin-type transmembrane glycoprotein, expressed in lymphatic endothelial cells and other cells such as macrophages and tumor cells." (PMID 30781402, 2019). "Our study shows that SZ168 is a blocking antibody to human PDPN that inhibits the interaction between tumor PDPN and platelet CLEC-2." (PMID 31208371, 2019). "Experimental evidence demonstrating the importance of the podoplanin–CLEC-2 interaction for tumor spread is ample and strong." (PMID 30736372, 2019). "There are contradictory results with respect to the involvement of podoplanin in tumor lymphangiogenesis." (PMID 30736372, 2019). "In this context, deletion of podoplanin attenuated tumorigenesis and formation of tumor-spheres in culture, which is compatible with TIC depletion." (PMID 30736372, 2019). "In comparison to three non-PPBC patients, who were all nulliparous, we observed increased PDPN+ LVD in the peri-tumor region from our PPBCs." (PMID 31244852, 2019). "Activation appeared to involve up-regulation of podoplanin in dermal fibroblasts, which plays a major role in the effects these fibroblasts have on tumor cells." (PMID 31233557, 2019). "Overall, the main conclusion from these experiments was that podoplanin promotes tumor progression through a variety of strategies encompassing different steps of the metastatic cascade." (PMID 30736372, 2019). "Podoplanin plays a role in tumour invasion and metastasis through its ability to remodel the actin cytoskeleton of tumour cells (Deepa, Angelin, Joseph, & Das, 2017), and it plays an important role in preventing cellular adhesion." (PMID 31452946, 2019). "In ACC tumours, high levels of podoplanin and low levels of E‐cadherin correlated with better survival (P = .022 and P = .021, respectively)." (PMID 31452946, 2019).